MELK (maternal embryonic leucine zipper kinase)
Diseases named in the same sentence as MELK in open-access papers (continued):
Sharing a sentence is not in itself a finding about the gene and the disease.
colon cancer (7 papers, 2015 to 2025). "hsa_circ_0101050 promotes colon cancer development by targeting the miR-140-3p/MELK axis." (PMID 41229443, 2025).
endometrial cancer (7 papers, 2013 to 2025). Primary or metastatic malignant neoplasm involving the endometrium (mucous membrane that lines the endometrial cavity). "Additionally, among the genes closely associated with UBE2T expression, genes like DTL, NUF2, and MELK may also contribute to the progression of endometrial cancer." (PMID 39367897, 2025). "Several treatment targets play a critical role in endometrial carcinoma progression, including maternal embryonic leucine zipper kinase (MELK), an enzyme frequently overexpressed in endometrial carcinoma tissues." (PMID 38848146, 2024). "Conversely, downregulated MELK expression reduces proliferation, migration, and tumorigenesis in endometrial carcinoma cells." (PMID 38848146, 2024). "MELK promotes endometrial cancer progression through activation of the mTOR signaling pathway." (PMID 39367897, 2025). "Among these, we found that two previously implicated stem cell associated markers, the disks large homolog 7 (DLG7, also known as DLGAP5) and the maternal embryonic leucine zipper kinase MELK transcripts were elevated in endometrial cancer specimens compared to controls." (PMID 23785665, 2013). "Moreover, MELK overexpression promotes endometrial carcinoma progression by modulating the E2F transcription factor 1 (E2F1) protein and activating the mTORC1 (mammalian transducer of regulated cAMP response element-binding protein) and mTORC2 signaling pathways." (PMID 38848146, 2024). "The MELK inhibitor OTSSP167 has shown potential in pre-clinical models for several cancer types, including endometrial cancer." (PMID 39596419, 2024). "High MELK expression correlates with histological subtype, higher grade, advanced clinical stage, decreased overall survival (OS), and reduced disease-free survival (DFS) in endometrial carcinoma." (PMID 38848146, 2024). "Interestingly, when analyzing the role of the Akt/mTOR signaling pathway in the tumorigenesis and stemness of cancer, we found previous studies indicating that high MELK expression can activate the mTORC1 and mTORC2/AKT signaling pathways and promote the development of endometrial cancer (EC)." (PMID 35440604, 2022).
pancreatic cancer (7 papers, 2019 to 2023). "Silencing of MELK significantly reduces pancreatic cancer development, as MELK promotes CDK1 involvement in the cell cycle and cell progression in cancers." (PMID 38144520, 2023). "ASPM, CCNB1, CDK1, MELK, OAS3, PPTG1 and TOP2A were thought to be significantly associated with shorter overall survival in pancreatic cancer patients." (PMID 36167975, 2022). "MELK is up-regulated in pancreatic cancer and other types of solid tumors and plays an important role in the formation and maintenance of tumor stem cells." (PMID 32548103, 2020). "Moreover, OTSSP167, the MELK-targeting compound, inhibits the growth of various human cancers, including breast, lung, prostate and pancreatic cancers." (PMID 32548103, 2020). "MELK inhibitor, OTS167, is reported to suppress tumor growth in breast, lung, prostate, and pancreatic cancer cell lines." (PMID 33801837, 2021). "Orally administrative MELK-targeting compound OTSSP167 inhibited the growth of different types of human cancer including breast, lung, prostate, and pancreas cancer." (PMID 31412643, 2019).
bladder cancer (6 papers, 2007 to 2025). "Downregulation of THAP10 reduces apoptosis, favoring uncontrolled proliferation, while MELK overexpression is linked to aggressive tumor behavior and poor outcomes in solid cancers, including bladder cancer." (PMID 40867248, 2025). "Previous reports have shown that MELK expression was correlated with shorter survival times in patients with oral squamous cell carcinoma, bladder cancer, or clear cell renal cell carcinoma." (PMID 36353126, 2022). "Recent studies have shown that MELK can improve the development of renal cell carcinoma and bladder cancer through accelerating the EMT process." (PMID 33962400, 2021). "First, the MELK expression level in bladder cancer was detected." (PMID 31821699, 2020). "We aimed to investigate the biological function of MELK and the therapeutic potential of OTSSP167 in human bladder cancer (BCa)." (PMID 31821699, 2020). "On the other hand, HT1197 (bladder) cancer cells, in which MELK expression was hardly detectable, revealed IC50 value of 97 nM, clearly implying the MELK-dependent growth-inhibition effect of this compound." (PMID 23283305, 2012). "Furthermore, our cDNA microarray data indicate that MELK is also up-regulated relatively frequently in bladder cancers, osteosarcoma and small cell lung cancers (data not shown)." (PMID 17280616, 2007).
oral squamous cell carcinoma (5 papers, 2021 to 2025). "Previous studies have shown that MELK expression correlates with increased metastatic potential and poor outcomes in cancers such as lung, esophageal, and oral squamous cell carcinoma." (PMID 40076867, 2025). "The aim of this study is to investigate the role of maternal embryonic leucine-zipper kinase (MELK) in EMT regulation in oral squamous cell carcinoma (OSCC)." (PMID 33962400, 2021).
small cell lung carcinoma (5 papers, 2007 to 2022). Small cell lung cancer (SCLC) is a highly aggressive malignant neoplasm, accounting for 10-15% of lung cancer cases, characterized byrapid growth, and early metastasis. "Maternal embryonic leucine zipper kinase (MELK), that plays a critical role in maintenance of cancer stem cells (CSCs), is predominantly expressed in various types of human cancer including small cell lung cancer (SCLC)." (PMID 26871945, 2016).
acute myeloid leukemia (4 papers, 2014 to 2020). Acute myeloid leukemia (AML) is a group of neoplasms arising from precursor cells committed to the myeloid cell-line differentiation. "High expression of MELK was observed in less differentiated human acute myeloid leukemia (AML) cell lines and AML blasts with complex karyotypes and was associated with worse clinical outcome." (PMID 32047721, 2020). "Here we report characterization of possible roles of MELK in acute myeloid leukemia (AML)." (PMID 25365263, 2014).
brain tumor (4 papers, 2006 to 2017). "Similar results were obtained with the macrocyclic thiazole antibiotic Siomycin A, initially identified as an inhibitor of the transcription factor FOXM1b and thereafter reported to reduce MELK expression in brain tumor stem-like cells in vitro." (PMID 28683086, 2017).
leukemia (4 papers, 2016 to 2021). A malignant (clonal) hematologic disorder, involving hematopoietic stem cells and characterized by the presence of primitive or atypical myeloid or lymphoid cells in the bone marrow and the blood. "Increased MELK expression was already reported in a variety of solid (breast, prostate, etc.)and hematological cancers (leukemia and multiple myeloma), and has been associated with a worse clinical outcome for these patients." (PMID 31740676, 2019). "We have previously reported that MELK is aberrantly expressed in AML cell lines and primary patient leukemia cells, and is associated with a poor prognosis." (PMID 33658483, 2021). "OTSSP167 is a potent MELK inhibitor and was shown to impair cancer growth in leukemia, myeloma, small cell lung cancer, neuroblastoma, prostate cancer, and kidney cancer cells." (PMID 31740676, 2019). "FOXM1 is a key transcriptional factor involved in the proliferation of cancer cells including leukemia cells that were very sensitive to both TOPK and MELK inhibitors." (PMID 26933922, 2016). "Thus, it is not surprising that high levels of MELK are detected in many solid tumors and in leukemia, where increased MELK expression correlates with poor prognosis and aggressiveness." (PMID 31861475, 2019).
medulloblastoma (4 papers, 2014 to 2024). A malignant, invasive embryonal neoplasm arising from the cerebellum. "Also, non-receptor tyrosine kinases such as the SRC-family kinases and serine/threonine specific kinases including aurora A and maternal embryonic leucine zipper kinase (MELK) have been implicated in medulloblastoma formation." (PMID 25216529, 2014). "EZH2 and MELK also have a similar relationship in medulloblastoma." (PMID 38183103, 2024). "Importantly, in vivo models of medulloblastoma displayed a significant survival benefit from the knockdown and pharmacological inhibition of MELK and EZH2, highlighting the relevance of these two proteins in brain tumor proliferation." (PMID 38183103, 2024). "In medulloblastoma models, phosphorylated EZH2, and its H3K27 methylation activity, were reduced upon MELK gene silencing." (PMID 38183103, 2024).
osteosarcoma (4 papers, 2007 to 2025). A usually aggressive malignant bone-forming mesenchymal neoplasm, predominantly affecting adolescents and young adults. "MELK has been identified as an adverse prognostic marker and therapeutic target in osteosarcoma." (PMID 38382096, 2024). "The overexpressed kinases in osteosarcoma, liposarcoma, and leiomyosarcoma are mainly serine/threonine kinases (BUB1, CKD4, HUNK, LKKK1, NEK2, PBK, PLK1, and PLK4), whereas TTK has a dual role (Tyrosine and serine/threonine kinase) and only MELK presents tyrosine phosphorylation activity." (PMID 40723917, 2025).
ovarian carcinoma (4 papers, 2015 to 2018). A malignant neoplasm originating from the surface ovarian epithelium. "The protein expressions of 5 hub genes (CDK1, TOP2A, CDC20, NCAPG, and MELK) are significantly up-regulated in ovarian cancer compared to normal tissues." (PMID 30453999, 2018). "Given the preferential upregulation of MELK in cancers and recent experimental data suggesting the positive role of MELK on cancer cell growth, MELK has been recognized as a potential therapeutic target for brain, colorectal, lung, and ovarian cancers." (PMID 25852826, 2015).
adrenocortical cancer (3 papers, 2021 to 2023). "In addition, MELK regulates cell cycle progression, leading to a worse prognosis in patients with adrenal cortical carcinoma and Wilms tumor, and it could be a novel target for cancer therapy." (PMID 36776306, 2023).
cervical squamous cell carcinoma (3 papers, 2021 to 2024). A squamous cell carcinoma arising from the cervical epithelium. "Cervical squamous cell carcinoma (CESC) showed the second highest levels of MELK expression among all other tumors compared." (PMID 35749404, 2022).
colitis (3 papers, 2023 to 2024). Inflammation of the colon. "In the AKT/IKK/P65 and ERK/IKK/P65 signaling pathways, studies have found that the expression of MELK is elevated in colitis patients and mouse models." (PMID 38965216, 2024). "In a recent study, the pharmacological inhibition of MELK was found to limit ferroptosis and inflammatory responses in colitis and colitis-triggered carcinogenesis." (PMID 37008632, 2023).
colorectal adenocarcinoma (3 papers, 2018 to 2021). The most common type of colorectal carcinoma. "MELK was overexpressed and highly phosphorylated in colorectal adenocarcinomas, and its expression was significantly correlated with tumor stage and lymph node metastasis." (PMID 32153633, 2020). "MELK promoted the occurrence and progression of colorectal adenocarcinomas." (PMID 34175839, 2021). "Importantly, we found that STRAP and MELK were overexpressed and highly phosphorylated in colorectal adenocarcinomas and their expression were significantly correlated with tumor stages." (PMID 29783958, 2018).
esophageal cancer (3 papers, 2019 to 2025). A primary or metastatic malignant neoplasm involving the esophagus. "MELK and PKMYT1 (a dark kinase gene) have been identified as promising therapeutic targets in multiple cancers, such as the brain, colorectal, breast, ovarian, and esophageal cancers, respectively." (PMID 33801837, 2021).
kidney cancer (3 papers, 2016 to 2018). Primary or metastatic malignant neoplasm involving the kidney. "A similar approach has already been proposed in kidney cancer cells, where combined targeting of MELK and another kinase, TOPK, was shown to have stronger growth‐suppressive effects than targeting either kinase on its own." (PMID 29437778, 2018). "In summary, we suggest that both TOPK and MELK are attractive molecular targets for kidney cancer treatment and they constitute a feedback loop with an oncogenic transcriptional factor FOXM1." (PMID 26933922, 2016). "The Oncomine database revealed that both TOPK and MELK genes are significantly up-regulated in kidney cancers." (PMID 26933922, 2016). "We examined expression levels of TOPK and MELK genes in kidney cancers through publically-available gene expression datasets." (PMID 26933922, 2016). "We first transfected kidney cancer cells with siFOXM1 and found that both TOPK and MELK mRNA levels were decreased in three kidney cancer cell lines compared with the cells treated with control siRNA." (PMID 26933922, 2016). "In this study, we investigated possible roles of TOPK and MELK in kidney cancer cells and found their growth promotive effect as well as some feedback mechanism between these two molecules." (PMID 26933922, 2016). "According to the Oncomine database, TOPK and MELK are upregulated in kidney cancer and considered as promising molecular targets because of their cancer-restricted expression patterns." (PMID 26933922, 2016). "Based on these findings, we investigated expression levels of TOPK and MELK in 16 kidney cancer cell lines by western blot analysis." (PMID 26933922, 2016). "We also revealed that the growth of kidney cancer was suppressed by either TOPK or MELK inhibition." (PMID 26933922, 2016). "To investigate the biological function of TOPK and MELK in kidney cancer cells, we used siRNA (small interfering RNA) to knockdown TOPK and MELK expression using three kidney cancer cell lines, VMRC-RCW, Caki-1, and Caki-2 in which TOPK and MELK were highly co-expressed." (PMID 26933922, 2016). "Similarly, our results in kidney cancer cells treated with the IC50 concentration of MELK inhibitor (OTS167) showed decrease of MELK and TOPK proteins as well as FOXM1 protein." (PMID 26933922, 2016). "Collectively, our results suggest that both TOPK and MELK are promising molecular targets for kidney cancer treatment and that dual blockade of OTS514 and OTS167 may bring additive anti-tumor effects with low risk of side effects." (PMID 26933922, 2016). "Small molecular compound inhibitors against TOPK (OTS514) and MELK (OTS167) effectively suppressed the kidney cancer cell growth, and the combination of these two compounds additively worked and showed the very strong growth suppressive effect on kidney cancer cells." (PMID 26933922, 2016). "Taken together, these results suggest that FOXM1 may function as a transcriptional factor that induces expression of TOPK and MELK genes in kidney cancer cells." (PMID 26933922, 2016). "We also demonstrated that the combination of OTS514 and OTS167 can effectively reduce the expression levels of TOPK, MELK and FOXM1, and decreased viability of kidney cancer cells." (PMID 26933922, 2016). "We then exogenously introduced FOXM1 expression vector into two kidney cancer cell lines and found the significant elevation of TOPK and MELK mRNA expression in the cells transfected with FOXM1 expression vectors, while no change was observed in those transfected with the mock control vector." (PMID 26933922, 2016). "Collectively, our assays implied that both inhibitors are very effective to suppress kidney cancer cell growth through reduction of TOPK, MELK, and FOXM1 proteins that may cooperatively constitute a critical signal pathway in kidney cancer cells." (PMID 26933922, 2016).
myeloma (3 papers, 2016 to 2019). "In summary, this study establishes elevated MELK expression in symptomatic MM and implicates its potential in promoting myeloma cell growth and drug resistance." (PMID 27540718, 2016). "Importantly, MELK inhibition induced potent and rapid apoptosis of MM PC and impaired outgrowth of malignant PC derived from presumptive myeloma stem cells in the peripheral blood." (PMID 27540718, 2016). "This experiment, while indirect, demonstrates that MELK inhibition may kill a circulating MM progenitor cell population and/or prevent myeloma stem cells from re-establishing the malignant MM PC population." (PMID 27540718, 2016). "We assessed the expression of MELK mRNA in malignant PC derived from MM patients and human myeloma cell lines (HMCL) and effects of the MELK inhibitor OTS167 on myeloma cells, including drug-resistant subclones." (PMID 27540718, 2016).
neuroblastoma (3 papers, 2018 to 2022). Neuroblastoma (NB) is the most common solid, extracranial childhood tumor. "In this study, using two microarray datasets of neuroblastoma (NB) patients, we identified that MELK expression is significantly correlated to poor overall survival, unfavorable prognosis, and high-risk status." (PMID 29416794, 2018). "Interestingly, the expression of 3 of these genes i.e. MELK, MYBL2 and PLK1 is remarkably highly correlated with FOXM1 expression levels in 200 neuroblastoma tumors (correlation coefficients >0.9) suggesting a very tight co-regulated transcriptional control." (PMID 30504901, 2018).
Obesity (3 papers, 2018 to 2025). Accumulation of substantial excess body fat. "Some of the hub genes identified were AURKA, MELK, and TKT for prenatal LOW vs HIGH nutrition, and CTSS and ITGB2 for late gestation malnutrition followed by early obesity development (LOW-HCHF and HIGH-HCHF vs NORM-CONV)." (PMID 33975549, 2021).
cervical tumor (2 papers, 2018 to 2021). "It seems that MELK has a regulatory effect on the mitosis of tumor cells as polyploidy occurs in cervical tumor cells." (PMID 34671205, 2021).
chronic lymphocytic leukemia (2 papers, 2019 to 2024). "Inhibition of MELK has shown potent anti-leukemic effects in chronic lymphocytic leukemia, making it a candidate therapeutic target." (PMID 38382096, 2024). "OTSSP167 is a maternal embryonic leucine-zipper kinase (MELK) inhibitor with anti-cancer effect reported in several tumors, as well as in chronic lymphocytic leukemia." (PMID 31660987, 2019).
esophageal adenocarcinoma (2 papers, 2021 to 2024). A malignant tumor with glandular differentiation arising predominantly from Barrett mucosa in the lower third of the esophagus. "In a cohort of 55 patients, two biopsies of esophageal adenocarcinomas exhibited a novel fusion gene as a result of a complex interchromosomal translocation of NPC1 and maternal embryonic leucine zipper kinase (MELK)." (PMID 34281263, 2021).
invasive ductal breast carcinoma (2 papers, 2014 to 2022). The most common type of invasive breast carcinoma, accounting for approximately 70% of breast carcinomas. "Furthermore, immunohistochemistry (IHC) assays revealed that both nuclear and cytoplasmic staining scores of MELK were significantly higher in invasive ductal carcinoma (IDC) tumors compared to ductal carcinoma in situ (DCIS) and normal breast tissues." (PMID 35749404, 2022).
lymph node metastasis (2 papers, 2018 to 2021). "Furthermore, the expression of MELK, but not STRAP, was associated with lymph node metastasis." (PMID 29783958, 2018). "Subsequently, we observed we that OSCC with lymph node metastasis had a stronger immunoreactivity than OSCC without lymph node metastasis, and the expression of MELK was higher in metastatic lymph nodes than in the original tumour." (PMID 33962400, 2021).